H19 (H19 imprinted maternally expressed transcript)
Diseases named in the same sentence as H19 in open-access papers (continued):
Sharing a sentence is not in itself a finding about the gene and the disease.
cancer (continued). "LncRNA H19 has been widely recognized for its aberrant expression profile and role in carcinogenesis, and it is suggested to be a novel biomarker for the diagnosis of cancer." (PMID 31752724, 2019). "In addition, there have been reports of loss of heterozygosity for IGF-II, H19, CTCF, and the IGF-IIR, which indicates that many epigenetic alterations to the locus are common in cancers." (PMID 31590432, 2019). "The other issue that suggests that the IGF-II/H19 might be fundamental to many cancers relates to the ancient metabolic role that this locus appears to serve." (PMID 31590432, 2019). "Quite a few studies had explored the clinical use of lncRNA H19 in cancer detection and diagnosis." (PMID 31016202, 2019). "Recently, some studies demonstrated that LncRAN H19 SNPs was related to cancer development." (PMID 31772651, 2019). "The levels of H19 increased in various cancers, such as gastric and gallbladder carcinomas." (PMID 31208095, 2019). "The mechanisms by which these SNPs regulate H19 expression and are involved in cancer are unclear." (PMID 30890582, 2019). "In this way, lncRNA H19 promotes stemness of cancer stem cells and oxaliplatin resistance of CRC." (PMID 31885581, 2019). "Studies in childhood solid tumors such as hepatoblastoma, Wilms tumor, and embryonic rhabdomyosarcoma supported this idea, as all three cancers often exhibited reduced H19 expression and had frequently lost the maternal 11p15 chromosomal region housing this gene." (PMID 31616462, 2019). "The oncogenic H19 is constitutively expressed in multiple cancer types including breast cancer." (PMID 31784542, 2019). "Although the lncRNA H19 has been implicated in the regulation of carcinogenesis and progression of various cancers, the exact role of H19 SNPs in UCC in the Taiwanese population remains unclear." (PMID 31013794, 2019). "With neoplastic transformation, the reactivation of inherent developmental programs could lead to the cancer cells hijacking the developmental role of IGF-II/H19, which then operates with the inherent metabolic role to promote cancer progression." (PMID 31590432, 2019). "Most of the components of the locus have been implicated in various cancers, but how IGF-II, preptin, HOTS, H19, 91H, miR-483, miR-675, IMPs, and the other components are integrated both during early development and in carcinogenesis will require considerably more work to elucidate." (PMID 31590432, 2019). "A recent study has indicated that lncRNA interactions with miRNA and mRNA—such as H19, MALAT1, and KCNQ1OT1, HULC, and HOTAIR—could be potential diagnostic and prognostic biomarkers in cancer." (PMID 31164794, 2019). "In contrast, there have been many studies regarding H19 and cancer." (PMID 31590432, 2019). "Although further studies are required to clarify this matter, we speculate that the involvement of H19 differs among cancer cell types due to the existing balance in the expression of H19, its target gene and proteins, and micro-RNAs." (PMID 30410672, 2018). "Importantly, aspirin suppresses E2-induced cancer stem-like characteristics through decreasing both ERβ and H19 expression." (PMID 30389909, 2018). "Accumulating evidence has shown that lncRNA H19 is up-regulated in various human malignant tumors." (PMID 29416703, 2018). "Notably, aspirin attenuates E2-induced cancer stem-like traits through decreasing both H19 and ERβ expression." (PMID 30389909, 2018). "Hence, studies like the H19-DTA in cancer therapy open the door for the use of lncRNA regulatory regions and the tissue specificity of these genes to do precision medicine in different types of cancer such as PCa." (PMID 29755696, 2018).
cancer (continued). "Therefore, H19 was proposed to serve as a biomarker for poor prognosis in various cancers with different types of predictive factors and clinicopathological features." (PMID 30154386, 2018). "Mechanistically, H19 triggered autophagy via SIRT1 to induce cancer chemoresistance." (PMID 30451820, 2018). "H19 involvement in invasion and/or metastasis has been demonstrated in several cancers." (PMID 30410672, 2018). "H19 expression is directly induced by c-myc in various cancers." (PMID 29416703, 2018). "H19 is situated on chromosome 11p15.5 and plays a key role in various cancers including HCC, where the abnormal expression of H19 is linked with late stages of cancer and poor DSF and outcome." (PMID 30105249, 2018). "Aberrant relaxation of imprinted H19 has been detected in a wide variety of cancers." (PMID 30154386, 2018). "Ablation of H19 antagonizes E2-induced cancer stem-like properties in PTC cells." (PMID 30389909, 2018). "Increasing evidence has shown that H19 may have either oncogenic or tumor suppressor properties based on its opposite expression changes in various cancers, including bladder cancer and gastric cancer, but the exact mechanism is unclear." (PMID 29062612, 2017). "Using human cancer cell lines as a model system, we show that metformin functions to alter DNA methylation in a genome-wide fashion and that this action is at least in part mediated by the H19/SAHH/DNMT3B axis." (PMID 27775072, 2017). "H19’s role as an epigenetic modifier may also be important in the study of a barrier in cancer treatment, chemotherapy drug resistance." (PMID 28933364, 2017). "Indeed, UCA1, PVT1 and H19 can serve as a molecular marker for lymph node metastasis in various cancers." (PMID 28410241, 2017). "The published results of H19 and POLR2E polymorphisms with cancer risk were also conflicted." (PMID 28159929, 2017). "These meta-analysis results showed that high H19 expression may serve as a poor prognostic indicator in cancer patients which were in line with our pooling analysis based upon the TCGA database." (PMID 27926484, 2017). "The expression of H19 may inhibit malignant transformation of trophoblast cells into cancer cells, as is supported by the fact that overexpression of H19 in trophoblast cells leads to reductions in proliferation, migration and invasion." (PMID 28653993, 2017). "Although further studies are needed, the targeting of H19 and miR-675 could provide novel opportunities in the treatment of cancer patients." (PMID 29099749, 2017). "Moreover, we also selected five representative disease lncRNAs (HOTAIR, MALAT1, H19, MEG3 and TUG1) that play key roles as oncogenic molecules associated with various cancers to investigate their occurrences at the top 5%-20% of the candidate lists." (PMID 28076842, 2017). "And in this study, we aim to investigate whether H19 could be detected in bone marrow and used as biomarkers for MM, and define the NF-κB-related mechanism responsible for its cancer-promotive function." (PMID 29273733, 2017). "Aberrant expression of H19 had participated in multiple cancers." (PMID 28159929, 2017). "However, most of these studies have focused on the role of H19 in cancer, but little work has been carried out on miR-675." (PMID 28212565, 2017). "We first evaluated the prognostic power of H19 in five female cancers." (PMID 27926484, 2017). "Hitherto, the mechanism by which H19 regulates cancer stem cells, remains elusive." (PMID 28102845, 2017). "Moreover, as an oncogenic lncRNA in multiple cancers, H19 functioned as miRNA sponge to lead to the de-repression of ZEB1 and ZEB2 genes in the mesenchymal cells." (PMID 29340065, 2017). "Thus, in the meta-analysis, we mainly focus on evaluating the association between HOTAIR, PRNCR1, H19, POLR2E polymorphisms and cancer risk." (PMID 28159929, 2017). "The maternally expressed and imprinted gene H19 is elevated in numerous cancers." (PMID 29113413, 2017).
cancer (continued). "H19 is involved in human breast cancer through interaction with protein, microRNAs, H19-derived miR-675-5p, and H19 antisense lncRNA (91H) but the study of these ncRNAs is not only restrained in cancer cell behavior." (PMID 29099749, 2017). "Similarly, lncRNA H19, which has been reported to be upregulated in diverse human cancers, was highly expressed in ACBP and ASLB treated cells (2.04-fold change, P < 0.05)." (PMID 29156779, 2017). "Therefore, disrupted paternal imprinting on H19 acts as an oncogenic driver in several cancers, including NSCLC." (PMID 29113413, 2017). "Furthermore, lncRNAs such as MALAT1, HOTAIR, and H19 were found to act as tumor suppressor genes or oncogenes in cancer development." (PMID 28146578, 2017). "H19 is highly expressed in mesenchymal-like cancer cells and primary CRC tissues." (PMID 27888635, 2017). "The abundance of H19 in plasma suggests that it plays a systemic role in cancer progression." (PMID 29088808, 2017). "Prior reviews cover topics as extensive as H19’s regulation or its broad role in cancer." (PMID 28933364, 2017). "These cancers also shared three seed genes (H19, MALAT1 and MEG3)." (PMID 28051121, 2017). "Furthermore, H19 can serve as a precursor of miR-675 and regulate carcinogenesis, progression and metastasis of several types of cancers." (PMID 27903964, 2017). "RUNX1-IT1, MALAT1, H19, and HOTAIRM1 have been widely associated with cancer in recent years." (PMID 28389671, 2017). "Therefore, our findings implicate that G-quadruplex-mediated transcription regulation of H19 gene would be an effective target for anti-cancer agent." (PMID 28367967, 2017). "The lncRNA H19, a known oncogene in various cancer types, tumorigenesis and cancer progression." (PMID 27888635, 2017). "H19 overexpression has been reported in various human cancers including GC." (PMID 29088808, 2017). "Moreover, c-Myc also activates H19 transcription in cancer by binding to the regulatory region in its gene." (PMID 27802187, 2017). "Targeting cancer by vector-based gene therapy with the help of H19 could also represent a potential approach for targeting RCC in the future." (PMID 27092491, 2016). "Some well-known cancer-associated lncRNAs, such as H19, XIST, HOTAIR, MALAT1, MEG3, HNF1A-AS1 and PVT1, have indicated oncogenic and/or tumor suppressive roles like protein-coding genes in various cancers." (PMID 27074572, 2016). "H19 is a paternally imprinted gene located at chromosome 11p15.5 that was widely studied in cancer biology even before lncRNAs had gained the attention of cancer researchers." (PMID 27686732, 2016). "Accumulating evidence in recent studies has consistently demonstrated that the expression levels of H19 are upregulated in a variety of cancer types, including gastric cancer, esophageal cancer colorectal cancer, breast cancer, bladder cancer, and hepatocellular carcinoma." (PMID 26872375, 2016). "In conclusion, this meta-analysis suggested that H19 might predict progression and metastasis in cancers." (PMID 27672656, 2016). "However, it is worth noting that these seemingly contradictory roles of H19 were found in different types of cancer." (PMID 26983719, 2016). "The H19 was a potential target for exploration of cancer drugs." (PMID 27825121, 2016). "Our results reveal a previously unknown link between H19 and glutathione metabolism in the regulation of cancer-drug resistance." (PMID 27193186, 2016). "To uncover the mechanism of H19 regulation in GBC, we discovered that H19 shared miR-342-3p response element with FOXM1, an important oncogene that has been reported to be associated with many cancers." (PMID 27716361, 2016). "Numbers of researches about H19 were done to explore the mechanism in cancers." (PMID 27672656, 2016).
cancer (continued). "During recent years we have developed a DNA-based drug (a plasmid vector) constructed from the H19 regulatory sequence (H19 promoter) that is used to drive the expression of Diphtheria toxin A chain (DT-A) specifically to the cancer cells that express the H19 lncRNA." (PMID 26623562, 2016). "H19 and miR-675 are up-regulated in many types of cancers and in response to the same EMT trigger." (PMID 26623562, 2016). "Further studies are needed to verify the clinical utility of H19 in human cancers." (PMID 27825121, 2016). "Therefore, we performed this meta-analysis to systematically summarize the relationship between H19 and cancers." (PMID 27672656, 2016). "Moreover, the increase in H19 in patient plasma in both studies was significantly reduced in postoperative samples, suggesting a direct correlation between cancer tissue mass and circulating H19 concentrations." (PMID 27189224, 2016). "Result by cancer type indicated that H19 expression was significantly related to distant metastasis in nongastrointestinal tumors (OR = 3.85, 95% CI = 1.31–11.36, P = 0.01, random-effect) and also in the gastrointestinal tumors (OR = 0.34, 95% CI = 0.15–0.78, P = 0.01, random-effect)." (PMID 27672656, 2016). "Higher H19 expression was positively correlated with worse survival in various cancers." (PMID 27825121, 2016). "Further studies are still needed to verify the clinical utility of H19 in human cancers." (PMID 27825121, 2016). "Several studies suggest that aberrant lncRNA H19 expression may contribute to the carcinogenesis of many cancers." (PMID 27486980, 2016). "LncRNA H19, as an imprinted gene, servers as an oncogene and was aberrantly increased in several cancers, and it might promote carcinogenesis via acting as competitive endogenous RNAs (ceRNA) or precursors of microRNAs." (PMID 27486980, 2016). "An lncRNA H19 known for more than two decades also functions in cancer and cancer stem cells." (PMID 26880946, 2016). "Interestingly, we observed one lncRNA H19, known to be over-expressed in several types of cancer, was dramatically down-regulated in cells treated with CKI." (PMID 27602759, 2016). "Additionally, we verified that different H19 expression levels in HGSC tissues showed strong correlation with cancer recurrence." (PMID 27193186, 2016). "Examples of lncRNA genes having roles in lung tumorigenesis are H19, metastasis associated lung adenocarcinoma transcript 1 (MALAT1), smoke and cancer-associated lncRNA-1 (SCAL1), lncRNA-LET, intronic ncRNA AK126698, BC-200 and hox transcript antisense intergenic RNA (HOTAIR)." (PMID 25884481, 2015). "LncRNAs fall into this category, and LncRNA H19 was identified as an miRNA sponge containing both canonical and non-canonical binding sites for the let-7 family of miRNAs that play important roles in development, metabolism and cancer." (PMID 26424084, 2015). "Collectively, H19 is one of the most pervasive dysregulated lncRNAs seen in human cancer, and to date it is one of only a few lncRNAs that feeds into a positive feedback loop with MYC, by being transcriptionally upregulated by MYC and post-transcriptionally disinhibiting MYC mRNA degradation." (PMID 27077133, 2015). "Similarly to H19, c-Myc can also induce the transcription of CCAT1, also known as CARLo-5 (cancer-associated region long noncoding RNA), transcription and its ectopic expression was able to promote CRC cell proliferation in vitro." (PMID 26064090, 2015). "In addition, we reported that various cancers that metastasized to the lung show high expression levels of H19 lncRNA." (PMID 25884481, 2015). "The significance of H19 LOI in cancer is not well understood." (PMID 25884481, 2015).
cancer (continued). "One of them was H19, which was strongly down regulated in smokers’ cancer tissues." (PMID 26159226, 2015). "H19 lncRNA is thus emerging as one of the key players in cancer biology." (PMID 25884481, 2015). "Indeed, our studies suggest that H19 participates in the invasion process of cancer cells; Forced expression of H19 improves HCC cell invasiveness in an in vitro assay." (PMID 26536864, 2015). "We found that H19 was highly expressed in mesenchymal-like cancer cells and primary CRC tissues." (PMID 26068968, 2015). "However, some have been reported playing critical roles in cancer, such as H19, GUCY1B2, MEG3 and AKR7L." (PMID 25928635, 2015). "A number of lncRNAs, such as HOTAIR, MALAT and H19 were found to be aberrantly expressed in a number of cancers and extensively characterized as important players affecting the hallmark events of carcinogenesis, such as proliferation, apoptosis, and metastasis." (PMID 25954300, 2015). "CASP8 and H19 have been previously associated with WTs, and H19 in particular has been associated with sporadic bilateral disease, whereas RB1, Mir-195 and TSPAN32 aberrations have not previously been identified in WTs, although detected in other cancers." (PMID 25763109, 2015). "Reconciliation of these findings may be provided by the hypothesis that H19 arbitrates diverse functions in different cancer types or at unique stages of metastasis." (PMID 25101115, 2014). "Another non-coding RNA up-regulated in liver metastasis as well as in many cancer types is H19." (PMID 23594791, 2013). "The role of H19 in cancer development has been a matter of debate since its discovery in 1990." (PMID 23965803, 2013). "Rather than being one of the highest expressed genes in embryogenesis and placental development, H19 is either highly expressed and/or manifests an aberrant allelic pattern of expression in most types of human cancer with marginal postnatal expression in most tissues." (PMID 23429271, 2013). "LncRNA H19 is most abundant in embryonic tissues, but its expression is reactivated in several types of human cancer, including breast, bladder, and gastric carcinomas, where its expression is negatively correlated with the cyclin-dependent kinase inhibitor (CDKi) p57kip2." (PMID 24305655, 2013). "We previously hypothesized that H19 comprises a corner stone of the embryonic molecular circuit that cancer cells call upon, which otherwise remain quiescent and are under strict control, but are activated under specific conditions." (PMID 23429271, 2013). "For example, H19 is strongly expressed in embryonic cells and in a wide-range of human cancers." (PMID 21489289, 2011). "The down-regulation of the maternally expressed tumour suppressing non-coding H19 RNA may leads to cancer in Wilms' tumour and many adult onset cancers." (PMID 21281512, 2011). "The present work shows the successful use of a double promoter expressing vector, carrying on a single construct two separate DNA sequences expressing the diphtheria toxin A-fragment (DTA), from two different regulatory sequences, selected from the cancer-specific promoters H19 and IGF2-P4." (PMID 21162716, 2010). "The human IGF2-P4 and H19 regulatory sequences are highly active in a variety of human cancers." (PMID 21162716, 2010). "Thus, the H19-DTA-P4-DTA vector exhibited augmented-than-additive in vivo anti-cancer activity, compared to the combined activity of both single-promoter constructs (H19-DTA and P4-DTA." (PMID 21162716, 2010). "Recent data suggested a role for H19 in promoting cancer progression, angiogenesis and metastasis." (PMID 19656414, 2009). "Although the oncogenic mechanism(s) of H19 needs further investigation, the fact that H19 is highly expressed in many types of tumors in a relatively high percentage of cases points to H19 as a target for cancer gene therapy." (PMID 17786216, 2007). "Therefore, if epitalon binds to and inhibits H1.3 in the cancer cells, H19 would be derepressed." (PMID 40908429, 2025).